ERBB2 (erb-b2 receptor tyrosine kinase 2)
Diseases named in the same sentence as ERBB2 in open-access papers (continued):
Sharing a sentence is not in itself a finding about the gene and the disease.
breast cancer (continued). "In addition, trastuzumab is often used in combination in HER2 or ErbB2 positive breast cancer patients." (PMID 33747560, 2021). "Thus, increased Hsp90-Hsc70 chaperone function in ErbB2-overexpressing breast cancers is a co-driver of oncogenesis and a therapeutic target." (PMID 34439093, 2021). "It is known that ERBB2 is closely associated with NR1D1, the gene that encodes REV-ERBα (a clock protein involved in the secondary clock TTFL), and high levels of NR1D1 have frequently been found in breast cancer patients." (PMID 34842634, 2021). "When both the H&E-ERBB2 score and histological grade were included in a logistic regression analysis as covariates, the H&E-ERBB2 score remained as an independent predictor of breast cancer ERBB2 status in the FinProg test set (P = 0.005) and also in the FinHer external test set (P < 0.001)." (PMID 33597560, 2021). "ERBB2 thus drives HER2 positive breast cancer cells towards a Warburg effect-like phenotype." (PMID 34685621, 2021). "Moreover, the serum ERBB2 extracellular domain is emerging as a cancer marker of HER2-positive breast cancer." (PMID 33947097, 2021). "Therefore, ERBB2 promotes ATG12 expression to increase autophagy leading to resistance of breast cancer cells to cell death induced by a chemotherapeutic drug or hypoxia." (PMID 33801244, 2021). "In this study, we demonstrated that DEPTOR functions as a positive regulator of ErbB2 in ErbB2-positive breast cancer cells, which may contribute to the development of human breast cancer." (PMID 33995662, 2021). "In the present study, the FISH assay corroborated that circ-ERBB2 was mainly located in the cytoplasm of HER2-positive breast cancer cells, prompting that circ-ERBB2 might function as a miRNAs "sponge" in the cytoplasm." (PMID 34732216, 2021). "Indeed, coamplification of STARD3 and HER2/receptor tyrosine-protein kinase erbB-2 (ERBB2) genes contributes to the proliferation and metastasis of breast cancer cells by increasing membrane cholesterol and thereby improving oncogenic signaling." (PMID 34572920, 2021). "In addition, in HER2- or ERBB2-enriched breast cancer, dimerization with HER3/ERBB3 elicits robust activation of PI3K and Akt, since HER3/ERBB3 possesses six docking sites for PI3K." (PMID 35578699, 2021). "In addition, previous studies have shown that ErbB2 can block autophagy initiation by modulation of Beclin 1 in breast cancer and Alzheimer’s disease, and regulate autophagic cell death by modulation of ATG4B expression in retinal pigment epithelium cells." (PMID 33854045, 2021). "In ERBB2+ breast cancer cells, which are resistant to Trastuzumab, a monoclonal antibody anticancer treatment, the depletion of CHD4 was shown to induce the cell’s sensitivity to this antibody by reducing ERBB2 signaling, affecting the autophagy process, and decreasing cell proliferation." (PMID 34142021, 2021). "As CHIP-dependent degradation of newly synthesized CFTR occurs in the ER, through ERAD, we asked whether a similar process accounts for CHIP-dependent degradation of newly synthesized ErbB2 in ErbB2-overexpressing breast cancer cells." (PMID 34439093, 2021). "Consistent with our genomic comparison between primary and metastasis, the ESR1 mutation is found by the mean SHAP value as the most predictive feature of metastatic breast cancer, followed by FGFR4 mutation, SOX2 amplification, ERBB2 mutation, and FGFR1 mutation." (PMID 34795255, 2021). "In addition to the expected ESR1 hotspot mutations, ERBB2 and NF1 were the genes, mostly mutually exclusive, with the greatest difference in mutational frequency between pre- and post-hormonal therapy for HR + HER2− breast cancers." (PMID 33477469, 2021). "Lapatinib, which is known as a small molecule tyrosine kinase inhibitor (TKI), targeted the kinase domain of ERBB2-approved for breast cancer patients and may be resistant because of this insertion mutant." (PMID 34396843, 2021).
breast cancer (continued). "Furthermore, treatment with entinostat, a class I histone deacetylase (HDAC) inhibitor, up‐regulates the miR‐125b levels in erbB2/erbB3‐positive breast cancer cells." (PMID 33332677, 2021). "Herein, deletion of endogenous Pparγ1 reduced ErbB2-induced mammary tumors." (PMID 33946495, 2021). "EGFR/ErbB2 are members of the epithelial growth factor receptor family, gefitinib and lapatinib are clinically proven effective in targeting NSCLC with EGFR mutation and ErbB2 + breast cancers respectively." (PMID 34108040, 2021). "Accordingly, in vivo and in silico analyses of human breast cancer confirmed that the amplification of ERBB2 in combination with the overexpression of p130Cas induces a higher proliferation rate and an increased number of distant metastases, as well as a correlation with poor prognosis." (PMID 34708040, 2021). "Collectively these studies suggest Pparγ1 may represent a useful target for coextinction strategies of ErbB2 induced breast cancer." (PMID 33946495, 2021). "ERBB2 is a member of the epidermal growth factor (EGF) receptor family of receptor tyrosine kinases, and its IgG autoantibody has been extensively assessed as a potential diagnostic biomarker for gastric cancer and breast cancer." (PMID 35140701, 2021). "ErbB2 is amplified or overexpressed in up to 25% of human breast cancers." (PMID 34439093, 2021). "We have previously shown that ECD protein is overexpressed in ErbB2+ breast cancers (BC)." (PMID 33941617, 2021). "The overexpression of ErbB2 leads to increased breast cancer metastasis." (PMID 33669783, 2021). "Moreover, in vivo assays further expounded that the circ-ERBB2 knockdown restrained the HER2-positive breast cancer growth and metastasis." (PMID 34732216, 2021). "Requirement of ECD for oncogenic traits of ErbB2-overexpressing breast cancer cells." (PMID 33941617, 2021). "Furthermore, ERBB2-induced treatment resistance in breast cancer is contributed to at least by specific upregulation of ATG12 (autophagy-related 12) which promotes autophagy." (PMID 33801244, 2021). "Thus, ErbB2 has served as a biomarker for breast cancer prognosis and a therapeutic target for cancer treatment." (PMID 33854045, 2021). "Using 2nd line HER2 inhibitor lapatinib resistant 3-dimensional model systems, we assessed the effects of the drugs on ErbB2 positive breast cancer spheroids and developed a high-throughput invasion assay for HER2 positive ovarian cancer organoids for further evaluation." (PMID 33939112, 2021). "Therefore, GPCR expression profiling was further done in tumors of a well-established transgenic animal model of human HER2+ breast cancer, Neu mice, which express an activated rat ErbB2/HER2 homologue selectively in the mammary gland." (PMID 34343132, 2021). "In this study, we found near 80% of the BRCA1-deficient mouse mammary tumors are ER and PR double negative, while 60% of the tumors show detectable expression level of ERBB2, which is inconsistent with the human BRCA1 related breast cancers." (PMID 34815798, 2021). "Besides ERBB2, other potentially actionable genes that have been found to be often amplified in breast cancer, including TNBC, are NOTCH1/2/3, MYC, FGFR1/2, and EGFR, with EGFR amplification associated with poor patients outcome." (PMID 34281208, 2021). "This study focused on ERBB2+ breast cancer cells and aimed to establish what type of EVs they release and whether Trastuzumab affects their morphology and molecular composition." (PMID 33809102, 2021). "In this report, we demonstrate the versatile applicability of the new MMTV-Flp strain to manipulate genes in a temporally and spatially controlled manner in the normal mammary gland, in luminal-type mammary tumors that overexpress ERBB2, and in a new KRAS-associated mammary cancer model." (PMID 34675248, 2021).
breast cancer (continued). "Resistance to ERBB2-targeted therapy including the use of trastuzumab, an anti-ERBB2 monoclonal antibody, and lapatinib, a small molecule kinase inhibitor of ERBB2 and EGFR, is associated with alternations of signal transduction pathways, apoptosis, and cell cycle control in breast cancer." (PMID 33801244, 2021). "Besides that, some somatic mutations of the ErbB2 gene, termed activating mutations, increasing ErbB2 phosphotyrosine kinase activity or dimerization effectiveness are found in ErbB2+ breast cancer patients." (PMID 34944558, 2021). "Furthermore, nuclear expression of ARID3B was positively related to ER status and negatively correlated with ERBB2 status, tumor grade and mitotic index in the breast cancer patients." (PMID 33592583, 2021). "Our findings related to morphology-based prediction of the ERBB2 status are in line with those from a recent study, in which a deep learning-based method was used to predict ERBB2 and a series of other biomarkers in breast cancer from H&E-stained tissue microarray spots." (PMID 33597560, 2021). "Gene expression pattern supports that OXTR overexpression induces ERBB2+ mammary tumors." (PMID 34099636, 2021). "This study supports p130Cas/ErbB2 complex as a potential breast cancer target and shows the druggability of this protein-protein interaction (PPI) that might benefit from a more advanced optimization effort for therapeutic applications." (PMID 34708040, 2021). "Different subtype composition could be one reason, e.g., more frequent ERBB2 amplification in human breast cancer may be due to more prevalent Her2-enriched subtype in humans than in dogs." (PMID 34344882, 2021). "The dysfunction of the ErbB2 (HER2) receptor plays a key role in breast cancer pathogenesis." (PMID 33806009, 2021). "Meanwhile, we used the specific probe of circ-ERBB2 for RNA pull-down assay to verify the miRNAs (miR-136-5p, miR-564, miR-198, miR-892b, miR-890 and miR-377-3p) that have been reported in breast cancer and might be regulated by circ-ERBB2." (PMID 34732216, 2021). "Notably, Hsp90 inhibitors exhibit selectively higher antitumor effects against ErbB2-overexpressing breast cancer cells and these effects are synergistic with ErbB2-targeted therapeutics Trastuzumab or Lapatinib." (PMID 34439093, 2021). "Indeed, among the patients with ERBB2/HER2-positive breast cancer, patients with the F/F158 genotype (46%) and F/V158 genotype (42%) have greater prevalence relative to those with the V/V158 genotype (12%)." (PMID 34502398, 2021). "A specific question related to breast cancer is therefore whether a CNN trained to predict the ERBB2 status of a tumor also could predict the efficacy of anti-ERBB2 adjuvant treatment." (PMID 33597560, 2021). "HER2/ErbB2 are potential targets in chemotherapy of HER2-positive (HER2+) breast cancer." (PMID 34790121, 2021). "The 21 breast cancers from 19 heterozygous LoF variant carrier cases were predominantly high-grade, invasive, ductal carcinomas (19/21) and hormone receptor-positive (16/21) of which three had ERBB2 amplification (HER2+)." (PMID 33980861, 2021). "We previously showed that ECD protein is overexpressed in ErbB2+ breast cancers (BC)." (PMID 33941617, 2021). "In contrast to the role in ER− breast cancer (basal-like and ErbB2+) summarized above, CD151 appears to be tumor suppressive in some cases, for example, during the development and growth of ER+ mammary tumors in the mouse mammary tumor virus (MMTV) promoter-driven Wnt1 oncogene model." (PMID 33919420, 2021). "Comparative RNA expression analysis of genes associated with receptor status in Study biopsy #2: ESR1 (ER), PGR (PR), ERBB2 (HER2) and AR, showed high RNA expression in relation to basal intrinsic subtypes from The Cancer Genome Atlas (TCGA) primary breast cancer cohort." (PMID 33772089, 2021).
breast cancer (continued). "Xu and colleagues found that alcohol could enhance the tumor-promoting role of breast cancer stem-like cells through the activation of ErbB2/p38γ-MAPK signaling pathway." (PMID 32014008, 2020). "Besides breast cancer, ERBB2 overexpression is also commonly detected in gastric, esophageal and endometrial cancers." (PMID 32793288, 2020). "Identification of MZF1 as an oncogenic target of PAK4, whose activity is important for invasiveness of ErbB2 positive breast cancer cells, suggests that PAK4 inhibitors might be useful for the treatment of cancers whose aggressiveness depends on MZF1." (PMID 31963147, 2020). "MZF1 is needed for the invasion of ErbB2-expressing breast cancer cells." (PMID 31963147, 2020). "Therefore, celastrol strongly synergized with ErbB2-targeted therapeutics trastuzumab and lapatinib, producing higher level of killing of ErbB2-overexperssing breast cancer cell lines SKBr-3 with substantially lower doses of celastrol." (PMID 33364939, 2020). "Search for “ERBB2” in this table shows that this gene, well known for its indications for treatment and prognosis in breast cancer, is included in 10 FDA-approved biomarker products—nine individual amplification markers and one panel, the Prosigna multigene prediction panel." (PMID 32142370, 2020). "Our recent work show that in HER2-related breast cancer, amplification of the ERBB2 locus may lead to SRCIN1 amplification, thus contributing to the biological heterogeneity of this breast cancer subgroup." (PMID 31285546, 2020). "In addition, the HER-2 (also known as ERBB2) oncogene can be amplified through a series of structural variations in approximately 20% of all breast cancers." (PMID 33168103, 2020). "Triple Negative Breast Cancer (TNBC) is an aggressive subtype of breast cancer (BC) associated with poor outcomes that lack the expression of hormone receptors and ERBB2." (PMID 32605193, 2020). "Most of the studies state that patients with ErbB2 overexpression cause lower overall survival rates in breast cancer patients in comparison to the non-over expressed ErbB2." (PMID 33093498, 2020). "Since ErbB2 breast cancer is driven by homodimerization and/or heterodimerization of the amplified ErbB2 with other ErbB receptors, the loss of ErbB family receptors may further promote MEDICA efficacy in suppressing ErbB2 breast cancer." (PMID 32695336, 2020). "Lysosomes have a central role in the induction of invasion by ErbB2 in breast cancer cells." (PMID 31963147, 2020). "Breast cancer is typically categorized into subtypes, depending on the expression of hormone receptors (estrogen, progesterone) and of human epidermal growth factor 2 (HER2/ERBB2)." (PMID 32532074, 2020). "Interestingly, our observations of 17-AAG induced ErbB2 downregulation from 5 ErbB2-positive breast cancer cell lines imply similar molecular features much akin to the endocytic degradation of EGFR." (PMID 32327714, 2020). "One of the driver genes in breast cancer is ERBB2, which is an indicator of tumor invasion." (PMID 33324444, 2020). "Combination of everolimus with exemestrane is an effective treatment for ER+/ErbB2- breast cancer." (PMID 32493414, 2020). "This suggests that a gene signature may have value in predicting targetable ERBB2 alterations including ERBB2mut in HER2− breast cancer." (PMID 32782013, 2020). "If proved in future clinical studies, the bifunctional activity of MEDICA in abrogating ErbB receptors and inhibiting mTORC1 activity may offer a novel treatment mode for mTORC1-driven cancers in general and ErbB2 breast cancer in particular." (PMID 32695336, 2020). "ERBB2-targeted therapies such as anti-ERBB2 antibodies (such as trastuzumab or pertuzumab) or tyrosine kinase inhibitors (such as lapatinib and neratinib) have been successfully used against these types of breast cancers." (PMID 32906686, 2020).
breast cancer (continued). "Human Epidermal Growth Factor Receptor 2 positive (HER2+) breast cancer is a subgroup defined by over-expression of the HER2 tyrosine kinase receptor, which transduces biochemical signals across the cell membrane and amplification of the HER2 gene, ErBb2." (PMID 33245725, 2020). "In the MA12 trial comprising 328 premenopausal patients with ER+ primary breast cancer of all histological subtypes, non-silent ERBB2 mutations occurred in 5.2% of patients (N = 17) and were adversely prognostic of OS (p = 0.0114)." (PMID 32782013, 2020). "It was recently reported that patients with ERBB2-negative breast cancer with the Pro1170Ala polymorphism variant exhibit a decreased survival outcome." (PMID 32332709, 2020). "Breast cancer is subdivided into three types based on receptors, including progesterone receptor (PR), estrogen receptor (ER), and the human epidermal growth factor receptor 2 (HER2, also known as ErbB2)." (PMID 32746451, 2020). "However, ERBB2 amplification was often observed as arm-level events or separate from pter-located GISTIC peaks, including ASPSCR1 and RNF213, which is in stark contrast to the minimal amplification of ERBB2 observed in human breast cancers (inlet)." (PMID 32680987, 2020). "For instance, and among others, ERK5 pathway is associated with increased metastatic activity in prostate and hepatocarcinoma cancers, to elevated growth of breast cancer cells, overexpressing the ErbB2/Her2 receptor or to chemoresistance of breast cancer or acute myeloid leukemia cells." (PMID 32209980, 2020). "ERBB2 levels spiked in metastatic breast cancer between 10.0 and 4.0 months pre-diagnosis." (PMID 33004987, 2020). "ErbB-2 is a member of the ErbB family and plays a vital role in breast cancer development." (PMID 32978480, 2020). "Following treatment with trastuzumab or a dual epidermal growth factor receptor (EGFR)/ErbB2 tyrosine kinase inhibitor (TKI; i.e., lapatanib), in a range of HER2 positive breast cancer cell lines, HER2 was downregulated, while the Notch activity was upregulated." (PMID 32575680, 2020). "ERBB2 β3‐αC deletions were only found in breast cancers and sensitive to EGFR/ERBB2 inhibitor." (PMID 32757330, 2020). "At molecular level, previous study has shown that HK2 is essential for tumor initiation and survival in Kras-driven mouse lung cancer and ErbB2-driven mouse breast cancer, indicating that HK2 could be important to regulate cancer stemness." (PMID 32195170, 2020). "Importantly, we observed that PERP, ITB1, GNAS2, and GNA13 are upregulated by trastuzumab in ErbB2-positive human breast cancer cells BT-474 and MCF-7/Her2-18 which indicates that the effect of trastuzumab on these proteins is not unique to one cell line." (PMID 33023655, 2020). "In the case of stageI–II ErbB2-positive breast cancer, the risk of local recurrence and therisk of distant metastasis are 2.7-fold and 5.3-fold higher, respectively, thanthat of a ErbB2-negative cancer." (PMID 32742732, 2020). "A microfluidic immunosensor was designed for ErbB2 detection, which is a breast cancer biomarker." (PMID 32695956, 2020). "While some studies suggest that overexpression of IGF-IR or phosphorylated IGF-IR is inversely associated with patient prognosis among all subtypes of breast cancer, another study reveals that IGF-IR is only inversely associated with prognosis in ErbB2-positive breast cancer." (PMID 32493414, 2020). "Hence, in spite of the advances accomplished in treating ErbB2 breast cancer, the ErbB2 challenge still remains an unmet need." (PMID 32695336, 2020). "In contrast, a feed-forward loop seems to dominate in ERBB2-positive breast cancer." (PMID 32448168, 2020). "Likewise, ERBB2 signaling activation within breast cancer cells enhances ERRα target gene expression." (PMID 31894856, 2020). "HER2 (HER2/Neu or ERBB2) is one of the most used protein biomarkers among breast cancer patients." (PMID 32719400, 2020).